RNU6-306P (RNA, U6 small nuclear 306, pseudogene)
Gene: Small nuclear RNA gene on chromosome 10 (21,564,471 to 21,564,577, reverse strand). Ensembl gene ENSG00000207347.
Homologues: Orthologues: chimpanzee U6 (98% identical), macaque U6 (94% identical), rat U6 (82% identical), pig U6 (74% identical), dog U6 (71% identical), guinea pig U6 (64% identical). Paralogues in human: RNU6-1192P (93% identical), RNU6-489P (93% identical), RNU6-28P (83% identical), RNU6-1011P (82% identical), RNU6-222P (82% identical), RNU6-774P (82% identical), RNU6-11P (81% identical), RNU6-1329P (81% identical), RNU6-37P (81% identical), RNU6-38P (81% identical), RNU6-43P (81% identical), RNU6-560P (81% identical), and 1288 more.